BLM (BLM RecQ like helicase)
Diseases named in the same sentence as BLM in open-access papers (continued):
Sharing a sentence is not in itself a finding about the gene and the disease.
retinoblastoma (2 papers, 2021 to 2023). A malignant tumor that originates in the nuclear layer of the retina. "Interestingly cells from cancer syndromes show either a maximal number of MRE11 foci from 10 min to 1 h after 2 Gy X-rays (e.g., retinoblastoma, tuberous sclerosis complex, and neurofibromatosis type 1) or the MRE11 foci are impaired (e.g., in BRCA1-, BRCA2-, BLM-, FANC-, and ATM-mutated cells)." (PMID 37626928, 2023).
schizophrenia (2 papers, 2015 to 2024). A major psychotic disorder characterized by abnormalities in the perception or expression of reality. "Based upon findings from similar studies of rare variants in schizophrenia, it is unsurprising that we did not implicate any individual gene, but we note that our most significant gene for all recessive genotypes (MAF ⩽1%) is BLM, which causes a known disorder (Bloom syndrome #210900)." (PMID 26196440, 2015).
adenoma (1 paper, 2016). A neoplasm arising from the epithelium. "Our interpretation of the observed reduction in adenoma numbers in the ApcMin/+;BLMTg model is that elevated levels of BLM/Blm reduce HR in the intestinal epithelia, thus suppressing LOH and hence loss of the wild-type Apc allele." (PMID 27413734, 2016).
Anxiety (1 paper, 2022). Intense feelings of nervousness, tension, or panic often arise in response to interpersonal stresses. "Loss of BLM-s causes abnormality in the electrophysiology and morphology of GCs and a disrupted vDG neural network, which could underlie Blm-s-null-associated anxiety and depression." (PMID 36163151, 2022). "Here, in line with the view that genetic factors are critical determinants of mood control, we present our findings to show that deficit of a BCL-2 (B-Cell Lymphoma 2) family member BLM-s (BCL-2 like molecule, short transcript isoform) causes anxiety- and depression-like behavior." (PMID 36163151, 2022).
astrocytoma (1 paper, 2021). "Another IDH-mutant grade 4 astrocytoma patient (CL0101) was found to have a monoallelic pathogenic nonsense BLM mutation (p.Q548X)." (PMID 34885201, 2021).
benign prostatic hyperplasia (1 paper, 2019). A non-cancerous nodular enlargement of the prostate gland. "Previous studies have shown that BLM is more highly expressed in PC tissue than in normal prostate and benign prostatic hyperplasia tissues and that BLM regulates protein phosphorylation." (PMID 31210839, 2019).
bile duct cancer (1 paper, 2019). "We also identified previous unknown associations such as a second hit in ATM of a patient with bile duct cancer and a second hit in BLM in a patient with thymoma." (PMID 31263571, 2019).
bladder tumor (1 paper, 2025). "We found that BLM lactylation at the K24 site was increased in E-resistant bladder tumor tissues and different E-resistant cell lines." (PMID 40634292, 2025).
brain tumours (1 paper, 2023). "Our findings of high BLM expression in GBMs and its roles in responses to chemotherapeutics provide a rationale for targeting BLM helicase in brain tumours." (PMID 37169803, 2023).
carcinosarcoma (1 paper, 2020). A malignant tumor composed of a mixture of carcinomatous and sarcomatous elements. "BLM, AURKA and PITX1 were upregulated in each subtype and were more significantly upregulated in carcinosarcoma tumours than endometrioid." (PMID 32899298, 2020).
depression (1 paper, 2022). "Although BLM-s or its isoforms BLM-l (VPS50) is not in the list of candidate genes and variants for major MDD studies, our analysis of UK biobank does reveal that human VPS50 rs2285505 and rs17147430 variants are statistically significantly associated with increased depression in mood domain." (PMID 36163151, 2022).
desmoid tumor (1 paper, 2024). A desmoid tumor (DT) is a benign, locally invasive soft tissue tumor associated with a high recurrence rate but with no metastatic potential. "In a small series of patients with desmoid tumors, disease-causing variants were identified in CHEK2, ERCC5, BLM, MSH6, and PALB2; however, none of these genes has been shown to be associated with increased risk of having desmoids." (PMID 38540414, 2024).
endometrial stromal sarcoma (1 paper, 2024). "Few studies have investigated ATM, BLM, and CDH1 gene mutations in high-grade endometrial stromal sarcoma." (PMID 39009979, 2024).
familial breast cancer (1 paper, 2009). "Other studies have analyzed BLM Thr298Met and small cell lung carcinoma risk and BLM Pro868Leu and familial breast cancer, but none of these polymorphisms showed any association with cancer risk." (PMID 19432957, 2009).
glaucoma (1 paper, 2023). Increased pressure in the eyeball due to obstruction of the outflow of aqueous humor. "Several mRNAs, such as BLM, Ubc, Ptgs2, and Jun, have been shown to be involved in cataract development; however, the role of differential mRNA expression in cataract progression in glaucoma patients remains unclear." (PMID 37131205, 2023).
HBOC syndrome (1 paper, 2020). "In conclusion, we detected a significantly high prevalence of PALB2, BARD1, and BLM mutations, with a low frequency of mutant CHEK2 in the current Japanese cohort of 568 patients with BRCA1/2 WT HBOC syndrome." (PMID 32566746, 2020).
invasive ductal carcinoma (1 paper, 2024). "patient: BRCA1 c.5266dupC het, p.Gln1756Profs*74 and BLM c.1642C>T het, p.Gln548Ter, which are known pathogenic variants; the patient was diagnosed with Grade 3 triple negative, invasive ductal carcinoma at the age of 32 years." (PMID 39148954, 2024).
laminopathies (1 paper, 2018). "On the other hand, the phenotypes generated by mutations affecting genes directly acting on DNA function, as mutations in the helicases WRN and BLM or in the polymerase polδ, share many of the traits of progeroid laminopathies." (PMID 29936894, 2018).
liver cancer (1 paper, 2020). An epithelial or non-epithelial malignant neoplasm that arises from the liver. "Next, Cox relative risk model is used to examine Whether NUF2 and BLM can become independent diagnostic influence factor for 95 patients suffering from liver cancer in our center." (PMID 32565735, 2020). "Therefore, we can think that nuf2 and BLM can provide independent prediction for liver cancer patients." (PMID 32565735, 2020).
lung adenocarcinoma (1 paper, 2023). A carcinoma that arises from the lung and is characterized by the presence of malignant glandular epithelial cells. "Interestingly, the expression of BRCA1, BRCA2, BLM and RAD51 was significantly associated with poor prognosis in lung adenocarcinoma." (PMID 37298484, 2023).
Majewski syndrome (1 paper, 2025). "Endocrine dysfunction, well reported in XRCC4-related MPD, is also observed in other DNA repair defects, including DNA2, BLM, NSMCE2-related MPD [MIM#615807, MIM#210900, MIM#617253], but also in other MPD such as Majewski syndrome." (PMID 40114033, 2025).
malignant glioma (1 paper, 2023). A grade III or grade IV glioma arising from the central nervous system. "Our results point out that the BLM helicase is a plausible target in malignant gliomas to sensitise cells to chemotherapeutics." (PMID 37169803, 2023). "We show that mRNA and protein expression of BLM is elevated in malignant gliomas, and high levels of BLM mRNA correlate with poor survival of GBM patients." (PMID 37169803, 2023). "The elevated expression of BLM in malignant gliomas correlated with the poor survival of patients (p < 0.0001)." (PMID 37169803, 2023). "Altogether, our results show that a BLM helicase, which is upregulated in malignant gliomas, is a new target in tumour cells, which may pave way to the development of specific BLM inhibitors." (PMID 37169803, 2023). "We found upregulated BLM mRNA levels in malignant gliomas, increased cytosolic localisation and poor survival of GBM patients with high BLM expression." (PMID 37169803, 2023). "In this study we demonstrate that BLM, a member of REQL helicase family, is upregulated in malignant gliomas and impacts GBM patient survival." (PMID 37169803, 2023).
migraine (1 paper, 2025). "Among these genes, the five most significantly associated with migraine were BBS4 (p = 3.60×10−6), PAM (p = 6.50×10−5), MICA (p = 9.60×10−5), BLM (p = 4.35×10−4), and GPATCH4 (p = 7.29×10−4)." (PMID 41261954, 2025). "SMR and INTACT confirmed the validity of BLM, C12orf76, GPATCH4, PAM, SERPINC1 for migraine, and ALMS1, GPATCH4, NCF2, SLC12A1, ZKSCAN8P1 for migraine with aura." (PMID 41261954, 2025). "The results of the SMR, colocalization, and INTACT sensitivity analyses provided further validation of BLM, C12orf76, GPATCH4, PAM, SERPINC1 as contraindicated drugs’ target genes for migraine, and ALMS1, GPATCH4, NCF2, SLC12A1, ZKSCAN8P1 for migraine with aura." (PMID 41261954, 2025).
nasopharyngeal carcinoma (1 paper, 2022). A carcinoma arising from the nasopharyngeal epithelium. "The c.2207_2212delinsTAGATTC variant is the predominant pathogenic BLM variant identified in Ashkenazi Jews, a 6-bp deletion/7-bp insertion in exon 10 of BLM, often (for brevity) designated blmAsh, which has recently been described in a BS patient with nasopharyngeal carcinoma later in life." (PMID 33219493, 2022).
ovarian insufficiency (1 paper, 2025). "Its interaction BLM also suggests that it may play a role in ovarian insufficiency, similar to other RAD51 family genes." (PMID 38996041, 2025).
rapadilino syndrome (1 paper, 2012). "While some mutations in RECQL4 also lead to loss of protein, both missense mutations and the deletion of exon 7 common in RAPADILINO syndrome stand in contrast to the truncations of WRN and BLM." (PMID 23238538, 2012).
recessive primary microcephaly (1 paper, 2017). "Exome analysis also showed heterozygous variants in three genes, ATR, MCPH1 and BLM, which are known causes of autosomal recessive primary microcephaly." (PMID 28464862, 2017).
Renal cyst (1 paper, 2025). A fluid filled sac in the kidney. "Based on the model, one might also predict increased renal cystogenesis in patients with deficiencies in G4-specific helicases, like BLM or FANCJ, however loss of those G4 DNA resolution activities results in severe phenotypes that may preclude identification of clinically significant renal cysts." (PMID 39747084, 2025).
sclerosing pneumocytoma (1 paper, 2022). "Mutations in other tumor-related genes were also identified in the sclerosing pneumocytoma, like PTEN, BRAF V600E, BLM, KMT2D, but with relatively smaller incidence than AKT1 and β-catenin." (PMID 35490241, 2022).
Simpson-Golabi-Behmel syndrome (1 paper, 2020). Simpson-Golabi-Behmel syndrome is a rare X-linked multiple congenital anomalies syndrome, characterized by pre- and postnatal overgrowth, distinctive craniofacial features, variable congenital malformations, organomegaly and an increased tumor risk. "In addition to the WRN−/− and BLM−/− ESC lines generated using CRISPR/Cas9, we also attempted shRNA-mediated WRN or BLM knockdown in primary adipose-derived stem cells and the Simpson-Golabi-Behmel Syndrome (SGBS) human preadipocyte line." (PMID 32367056, 2020).
cancer (195 papers, 2005 to 2026). A tumor composed of atypical neoplastic, often pleomorphic cells that invade other tissues. "The BLM gene is being investigated as a BC susceptibility gene and has been associated with survival following immunotherapy across multiple cancers." (PMID 40941673, 2025). "BLM mutations are associated with extreme cancer susceptibility in AML patients in both groups and in ALL patients in the young group." (PMID 38392574, 2024). "Deletion of BLM is known to precipitate Bloom Syndrome, in which patients exhibit genomic instability and an increased susceptibility to various cancers including prostate, lung, and breast cancer." (PMID 38806577, 2024). "We analyzed 10,967 cancer samples from the cancer genome atlas (TCGA) database and found that BLM mutation was associated with increased TMB and more immune‐active tumor microenvironment." (PMID 38124443, 2023). "BLM mutation is a potential biomarker for immunotherapy efficacy prediction and patient stratification across multiple cancer types." (PMID 38124443, 2023). "A total of 10,967 cancer samples from the cancer genome atlas database were analyzed, 1.6% of which harbored BLM somatic mutations." (PMID 38124443, 2023). "Initially, the co-expression of RECQs on the genome level was investigated in pan-cancer, revealing a robust association between BLM and RECQL4." (PMID 37626815, 2023). "Cancer patients with BLM mutations had higher complete response and partial response rates, but lower progressive disease rate than BLM nonmutant patients." (PMID 38124443, 2023). "Mutations in RecQ helicases (including BLM that causes the BS) result in autosomal recessive syndromes characterized by accelerated aging symptoms and cancer incidence." (PMID 37796556, 2023). "BLM encodes a RecQ DNA helicase that regulates genomic stability, and its mutations are associated with increased cancer susceptibility." (PMID 38124443, 2023). "BLM mutations can lead to genomic instability and increase cancer susceptibility, which is the pathological mechanism of the autosomal recessive human disease called bloom syndrome." (PMID 38124443, 2023). "Existing knowledge on CTE suggests that mutations in RecQ helicases such as BLM result in accelerated aging symptoms and cancer incidence." (PMID 37796556, 2023). "BLM inhibits double-strand breaks during DNA replication that can increase cancer predisposition in cell lines." (PMID 35626643, 2022). "Further studies are needed to better understand these polymorphisms in BLM and their influence on cancer risk and prognosis." (PMID 35782872, 2022). "Surprisingly, this computational analysis allowed us to identify in silico various critical players implicated in cancer processes, such as mTOR, BLM, MET, AMPK, and p130 (RBL2), as novel SMYD3 interactors." (PMID 35495117, 2022). "Perhaps it is possible that BLM mutation results in genomic instability, affecting its interaction with its binding partners to predispose a person to cancer." (PMID 35267530, 2022). "Increasing evidence suggests that BLM is involved in DSB repair; in accordance with this, the loss function of BLM in cancer cells causes hypersensitivity to DNA-damaging agents that directly or indirectly generate DSBs." (PMID 34606619, 2021). "We conclude that the BLM helicase domains are the primary mutational targets in both cancer and the germline, with predicted impact on its helicase activity." (PMID 34966786, 2021). "The involvement of WRN, BLM, and RecQL4 family members has been determined in the pathogenesis of well-defined genetic disorders with an elevated risk of cancer." (PMID 34164337, 2021). "Since BLM abnormalities are associated with genome instability, evidence accumulates in various cancers." (PMID 32565735, 2020). "Mutations in the BLM gene lead to patients often being affected by cancers before they reach adulthood." (PMID 31795919, 2019).
cancer (continued). "Bi-allelic mutations in the BLM gene result in Bloom's syndrome (BS) characterized by a pronounced predisposition to all types of cancer and certain features of accelerated aging." (PMID 29998112, 2018). "BLM is mutated in Bloom syndrome, an inherited genomic instability disorder similar to Fanconi anemia in its childhood cancer predisposition as well as the presence of aberrant chromosome structures." (PMID 28239445, 2017). "This probe was subsequently used to detect mutations occurring at the Y974Q975 region of BLM in human cancer." (PMID 27083049, 2016). "BLM deficiency results in major genomic instability—a hallmark of most cancers and a factor that escalates the cancer frequency in those with BS." (PMID 27413734, 2016). "We found there were deletion and/or point mutations in the Y974Q975 region within the motif VI of BLM protein that were documented in human cancers." (PMID 27083049, 2016). "Although loss-of-function BLM alleles have been associated with human cancers genome-wide association studies have yet to identify alleles associated with longevity." (PMID 27413734, 2016). "People carrying mutations in the BLM gene are predisposed to different types of cancer and have a shortened lifespan." (PMID 25477524, 2015). "Meanwhile, two different single-nucleotide variants affecting intron regions of RAD51 were shown to increase cancer risk in carriers of mutations in the BLM gene." (PMID 25539919, 2015). "Analyses of the familial histories for cancer revealed that carriers of a heterozygous deleterious BLM mutation most likely have a low-to-moderate penetrant risk for developing CRC." (PMID 26358404, 2015). "Mutations in the human RecQ helicase gene BLM lead to BS, a hereditary disease associated with genomic instability and a predisposition for cancer." (PMID 24174542, 2014). "This suggests that while loss of mammalian BLM and overexpression of Myc both result in genomic instability and cancer, the mechanisms by which they do so are distinct." (PMID 24040302, 2013). "Three of the human RecQ helicase disorders with mutations in WRN, BLM and RecQL4 helicases exhibit premature aging and cancer susceptibility owing to perturbations in DNA replication, transcription, recombination and repair." (PMID 23894508, 2013). "The fact that BS patients are predisposed to almost all forms of cancers can be interpreted to indicate that certain functions common to neoplastic transformation process is being regulated by BLM." (PMID 21050475, 2010). "BLM helicase has attracted much attention due to the hyper-recombinogenic phenotype of BS patients and their predisposition to almost all forms of cancers known to human." (PMID 21050475, 2010). "The impact of age on the associations between genetic markers of the BLM-complex and cancer risk was evaluated." (PMID 19432957, 2009). "The strongest genetic risk marker was found in BLM, i.e., the variant allele of rs2532105, which showed a statistically significantly increased risk for three out of four cancer forms analyzed." (PMID 19432957, 2009). "Consistent with this, BLM deficiency promotes anchorage-independent growth of non-cancer cells." (PMID 40355560, 2025). "Mutations in BLM that cause this intermediate phenotype could lead to increased risk of cancer or other adverse health impacts in humans." (PMID 36747637, 2023). "Indeed, the key role of BLM is well know, and alterations in this protein is linked to different diseases including cancer." (PMID 36177351, 2022). "Another study has analyzed derivatives of ML216 that seem highly specific allosteric inhibitors of BLM, that could be used to cause highly cytotoxic BLM-DNA complexes to kill cancer cells." (PMID 36569948, 2022). "Furthermore, SWS1–SWSAP1-SPIDR drives the high level of sister-chromatid exchange, promotes long-range loss of heterozygosity often involved with cancer initiation, and impels the poor growth of BLM helicase-deficient cells." (PMID 34253720, 2021).